MMP9 (matrix metallopeptidase 9)
Diseases named in the same sentence as MMP9 in open-access papers (continued):
Sharing a sentence is not in itself a finding about the gene and the disease.
glioblastoma (continued). "We found that parthenolide suppresses both tumour cell-induced angiogenesis and expression of the NF-κB targets, i.e., VEGF and MMP-9, in glioblastoma cells." (PMID 23039130, 2012). "Using experimental and bioinformatic approaches, we selected miR-211, a commonly downregulated miRNA, and analyzed its relationship to the expression of glioblastoma antigen (MMP-9), which is also a potential target of miR-211." (PMID 23183822, 2012). "This interaction network has the potential to shed new light on our understanding of the role played by MMP-9 in invasive glioblastomas." (PMID 16901352, 2006). "The GSK3β inhibitor AR-A014418 effectively counteracted the effects of GAD1 knockdown, suppressing the enhanced proliferation, cell cycle progression, and invasion of glioblastoma cells, while also reducing the expression of p-GSK3β, β-catenin, Cyclin D1, and MMP9." (PMID 41844572, 2026). "Moreover, low-expression of MMP9 was a favorable prognostic factor for primary glioblastoma, and it was thought that the glioblastoma with MMP9 low-expression would benefit more from radiotherapy combined with TMZ chemotherapy than radiotherapy alone." (PMID 41438689, 2026). "Recent studies indicate that MMP-9 is expressed differently across glioblastoma locations." (PMID 41573658, 2025). "Elevated intra-tumoral and serum MMP-9 levels, but not its activity, were associated with reduced overall survival in glioblastoma and BM patients (15.8 versus 8.4 months, p=0.022)." (PMID 41573658, 2025). "Additionally, blood samples were collected from healthy volunteers (n=23) to compare serum MMP-9 levels with those of the glioblastoma and BM patient groups." (PMID 41573658, 2025). "The role of intra-tumoral MMP-9 in glioblastoma has been highlighted in numerous studies." (PMID 41573658, 2025). "In glioblastoma, MMP-9 helps tumor cells escape from the hypoxic tumor core." (PMID 41573658, 2025). "A previous study also showed that curzerene could inhibit the migration and invasion of glioblastoma cell lines by downregulating MMP9 and EMT." (PMID 38166788, 2024). "Over 50% of the glioblastomas examined exhibited MMP-9 immunoexpression." (PMID 39684754, 2024). "Moreover, it was found that quercetin exerted promising activity in vitro against human glioblastoma cells (U251) by reducing the expression of matrix metallopeptidases MMP-9 and MMP-2." (PMID 39478959, 2024). "In the current study, MMP-9 expression was present in 54.5% of the glioblastomas examined." (PMID 39684754, 2024). "Additionally, engineering tumor cells to express MMP-9, which degrades type IV collagen, has been shown to enhance the spread of oHSV in both spheroid and xenograft models of glioblastoma." (PMID 39845957, 2024). "Additionally, patients with glioblastomas showing low MMP-9 expression were generally younger and had higher rates of MGMT promoter methylation and IDH1 mutations compared to patients with glioblastomas with high MMP-9 expression." (PMID 39684754, 2024). "Similarly, a neuronal miRNA-sensitive, EGFR-targeted oncolytic herpes simplex virus (oHSV) equipped with an MMP-9 transgene demonstrated improved intratumoral spread, oncolysis, and survival rates in a glioblastoma xenograft model." (PMID 39845957, 2024). "Consistent with our findings, data from a phase 3 study of Bevacizumab in newly diagnosed glioblastoma showed that baseline plasma MMP9 predicts overall survival (OS) benefit from Bevacizumab, where patients with lower MMP9 (<quartile 1) derived a significant 5.2-month OS benefit from Bevacizumab42." (PMID 38773224, 2024).
glioblastoma (continued). "Furthermore, MMP-9 activity also reduced in glioblastoma cells (GBM 8901) after treatment with different concentrations of naringenin, an ingredient of citrus that is also well represented in grapes." (PMID 39591310, 2024). "Moreover, JICD1-TWIST1-MMP2 and MMP9 axes were significantly correlated with clinical outcome of glioblastoma patients." (PMID 38092725, 2023). "Longitudinal increases in MMP-9 were weakly associated with shorter survival in glioblastoma patients, but they were not independently associated with survival after adjusting for age, extent of resection, and performance status." (PMID 36765669, 2023). "In conclusion, the baseline plasma level of MMP9 may be predictive of the efficacy of bevacizumab for patients with newly diagnosed glioblastoma." (PMID 34980260, 2022). "Moreover, a correlation between plasma expression of MMP9 and anaplastic glioma activity was previously reported, reinforcing the link between this circulating marker and the glioblastoma process." (PMID 34980260, 2022). "To explore the relationship between MMP9 plasma level and intratumoral glioblastoma biology, we analyzed the plasma expression of this marker before and after surgical resection of glioblastoma and its concomitant tumor expression in a prospective cohort of 38 patients." (PMID 34980260, 2022). "Taken together, these results suggest that plasma MMP9 is specifically released by glioblastoma, is not only linked to brain alteration and is not correlated to angiogenic or invasive markers." (PMID 34980260, 2022). "MMP-9 has been considerably involved in glioblastoma progression." (PMID 35221898, 2022). "Our results suggest that MUC4, along with MMP9, might account for glioblastoma progression, representing potential therapeutic targets, and suggesting the ‘MUC4/MMP9/EGFR axis’ may play a vital role in glioblastoma diagnostics." (PMID 36400876, 2022). "In the present study performed in a large prospective international multicentric phase III trial, for the first time to our knowledge, we identified MMP9 plasma level as a biomarker predictive of bevacizumab efficacy in patients with newly diagnosed glioblastoma." (PMID 34980260, 2022). "Previous reports have evidenced that K858 inhibits MMP-9 expression in human glioblastoma cells." (PMID 36290354, 2022). "On the basis of these preclinical results, we can hypothesize that MMP9 released by tumor-infiltrating neutrophils may increase VEGFA availability in the glioblastoma microenvironment, exceeding the ability of bevacizumab to trap it." (PMID 34980260, 2022). "The pattern of expression of MMP9 in glioblastoma remains controversial." (PMID 34980260, 2022). "Finally, independently of the immune system, the involvement of MMP9 in VEGFA release was also reported in a preclinical model of glioblastoma, highlighting its potential central role in the initiation and promotion of angiogenesis." (PMID 34980260, 2022). "The correlation analysis observed that SCIN positively correlated with the expression of MMP2 (Spearman correlation coefficient r = 0.357, p < 0.001) and MMP9 (Spearman correlation coefficient r = 0.356, p < 0.001) in TCGA RNA seq datasets for glioblastoma and low-grade glioma (TCGA GBMLGG)." (PMID 36291348, 2022). "Glioblastoma growth, hypoxia, and angiogenesis have been shown to be associated with mesenchymal marker expression including MMPs, and more especially MMP-2 during blood vessel reorganization and MMP-9 during invasion." (PMID 33937253, 2021). "MMP9 degrades Type IV collagen which is present in the ECM of glioblastoma multiforme (GBM)." (PMID 34206677, 2021). "LY294002 was reported to inhibit MMP9 expression and invasion of glioblastoma (C6) cells." (PMID 34209215, 2021). "Wang et.al reported that EIF4A3 could bind to the MMP9 mRNA transcript, facilitate circMMP9 cyclization and enhance circMMP9 expression in glioblastoma multiforme." (PMID 32264877, 2020).
glioblastoma (continued). "Glioblastoma cells promote their mobility, invasion, and metastasis through degradation of the extracellular matrix (ECM) mediated by tumor-associated matrix metalloproteinases (MMPs), such as MMP-2 and MMP-9." (PMID 32074974, 2020). "We found that CD147 in glioblastoma EVs played a role in increasing active MMP9 release by astrocytes, which could be blocked by CD147 knockout." (PMID 32033611, 2020). "Moreover, altered extracellular matrix proteins in glioblastoma induce the up-regulation of Matrix metalloproteinase-9 (MMP9) and Metalloproteinase inhibitor 1 (TIMP1) proteins that disrupt normal angiogenesis and promote tumor invasion." (PMID 31357616, 2019). "In view of our data, it is reasonable to infer that the inhibitory effect of α-H on glioblastoma cell migration and invasion may be associated to MMP-2 and MMP-9 downregulation." (PMID 31551765, 2019). "An increase in MGMT and MMP9 levels showed slightly poor prognoses of glioblastoma (p > 0.05)." (PMID 31653034, 2019). "Overexpression of MMP-2 or MMP-9 strengthens EMT process in glioblastoma." (PMID 29423667, 2018). "We observed that the expression of apoptosis-related factors (BIM, BAX and cleaved CASPASE3) and an invasion-related factor (E-CADHERIN) were higher, while the expression of related invasion factors (TWIST1, SNAIL and MMP9) were lower in glioblastoma cells with HDAC1-shRNA infection." (PMID 28624794, 2017). "miR-455, which locates at the protein-coding gene Col27a1, has been reported to be involved in early chondrogenic differentiation regulation, down-regulation of MMP-9 during exercise, hypoxia signaling and acquired temozolomide resistance in glioblastoma cells." (PMID 28538837, 2017). "There was positive correlation between the miR-148a levels in 10 freshly collected glioblastoma samples with MMP9 (r = 0.674, P < 0.001) and VEGF mRNA levels (r = 0.748, P < 0.001), the DNA-binding activity of NF-κB (r = 0.895, P < 0.001), and p-Smad3 expression (r = 0.754, P = 0.001)." (PMID 25971746, 2015). "In contrast, siRNA down regulation of gelatinase B/MMP-9 expression induces apoptosis in human glioblastoma cells in association with Fas death receptor-mediated caspase 3 and caspase 8 cleavage, implicating gelatinase B/MMP-9 in protecting glioblastoma cells against Fas ligand-mediated apoptosis." (PMID 24473089, 2014). "We found that parthenolide treatment inhibits both glioblastoma cell invasion and MMP-9 expression." (PMID 23039130, 2012). "Consequently, the reduction of MMP2 and MMP9 by Ad-CALR/MAGE-A3 will attenuate the metastatic potency of glioblastoma cells." (PMID 22293781, 2012). "It is tempting to hypothesize that in glioblastoma cell lines U373 MG, S1P induces invasion via cross-talk between pathways that include uPA, MMP-9, NRG-1, and VEGF." (PMID 16901352, 2006). "We found that regulation of uPA, NRG-1 and MMP-9 by S1P could be a key player in the invasion of glioblastoma cells." (PMID 16901352, 2006). "Additionally, intra-tumoral and sera MMP-9 may help identify glioblastoma and BM recurrence or progression." (PMID 41573658, 2025). "For instance, TTFields combined with RT effectively suppress cell migration and invasion in glioblastoma multiforme (GBM) cells by inhibiting proteins such as MMP-9 and vimentin." (PMID 39881333, 2025). "Circulating MMP9 is released by glioblastoma-infiltrating neutrophils, suggesting that antiangiogenic resistance could be related to a specific immunological glioblastoma profile, thus opening new perspectives in the development of therapy for glioblastoma." (PMID 34980260, 2022). "Bevacizumab (Bv), which targets on vascular endothelial growth factor (VEGF), a factor that recruits neutrophils expressing proangiogenic matrix metallopeptidase 9, is frequently used for glioblastoma (GBM) patients." (PMID 32970873, 2021).
glioblastoma (continued). "In glioblastoma, remodeling, and degrading of the ECM is observed since Matrix metalloproteinases (MMPs), more specifically MMP-2 and MMP-9, are released into the extracellular space." (PMID 41208963, 2025). "Astrocytes then become activated and start secreting elevated amounts of chemokines (e.g. IL-6), enhancing glioblastoma cell invasion and tissue infiltration by increased production MMPs, especially MMP-2 and MMP-9." (PMID 41208963, 2025). "As of 2025, nanoparticle-based delivery systems are being explored to improve MMP inhibitor efficacy, particularly in glioblastoma, where MMP-2 and MMP-9 drive ECM degradation and tumor invasion." (PMID 41303525, 2025). "In glioblastoma, curcumin inhibited STAT3 phosphorylation, reducing MMP-9, Snail, and Twist expression, and suppressed MMPs via MAPK inhibition." (PMID 40430278, 2025). "In conclusion, our study demonstrates that Calanquinone A exerts potent antitumor effects against glioblastoma multiforme by inhibiting cell viability, proliferation, and migration through suppression of the STAT3/c-Myc and STAT3/MMP9 signaling pathways." (PMID 40759869, 2025). "Studies in glioblastoma have demonstrated that EGFRvIII expression directly regulates the release of MMP2 and MMP9, leading to ECM breakdown and enhanced tumor invasiveness." (PMID 40472740, 2025). "We examined the effects of sodium fluoride (NaF) exposure on the migratory and invasive abilities of the U-87 human glioblastoma cell line, assessing levels of metalloproteinases MMP-2 and MMP-9 secreted by these cells." (PMID 39684484, 2024). "The majority of IDH-1 wild-type glioblastomas (57.5%, 23/40) exhibited MMP-9 immunoexpression, in contrast to IDH1 mutant glioblastomas, where MMP-9 immunoexpression was significantly lower (1/4)." (PMID 39684754, 2024). "Treatment with chrysomycin-A significantly inhibited the growth of glioblastoma cells and weakened the ability of cell migration and invasion by downregulating the expression of slug, MMP-2, and MMP-9." (PMID 38396785, 2024). "Supporting these outcomes, in-vitro studies showed the capability of CAR to decrease the MMP-9, MMP-2, and ROS in human glioblastoma and human mesenchymal stromal." (PMID 37666857, 2023). "The link between the survival of glioblastoma patients and their MMP-9 level of serum-derived sEVs is revealed in our article; hence, the identification of sEVs’ MMP-9 is of great importance." (PMID 36765669, 2023). "Recently, inhibition activation of A2BAR downregulated matrix metalloproteinase-9 (MMP-9) activity and EMT expression in glioblastoma stem-like cells." (PMID 36901855, 2023). "Chr-A treatment significantly inhibited the growth of glioblastoma cells and weakened the ability of cell migration and invasion by down regulating the expression of slug, MMP2 and MMP9." (PMID 36234681, 2022). "We therefore evaluate the clinical relevance of EGFR, MMP9, and MUC4 proteins for glioblastoma diagnosis and prognosis." (PMID 36400876, 2022). "Taken together, these results suggest that baseline plasma MMP9 level was predictive of the benefits of bevacizumab for PFS and OS in patients with newly diagnosed glioblastoma." (PMID 34980260, 2022). "Analysis of exosomes from glioblastoma cells showed that they are enriched with the proangiogenic factors VEGF, angiogenin, TGFβ, IL-8, IL-6, MMP2, MMP9, TIMP-1, TIMP-2, and CXCR4." (PMID 35740619, 2022). "Though MMPs are not typically viewed as important metabolic modulators, there is emerging evidence that MMP-2, MMP-9, and MMP-14 are potent modulators of cholesterol metabolism, a crucial pathway in glioblastoma growth and invasion." (PMID 34277624, 2021). "Other important ECM-binding proteins and/or modifying enzymes in glioblastoma cells are CD44 (HA receptor), matrix metalloproteinase-9 (MMP9), and hyaluronidases 1/2/3 (Hyal 1/2/3)." (PMID 34070023, 2021).
glioblastoma (continued). "It was found out also that fucoxanthin possess a capacity of human glioblastoma cell inhibition and the protein levels of MMP-2 and MMP-9 was significantly suppressed after incubation of glioma cells with fucoxanthin at the concentration of 25 and 50 μM." (PMID 34440090, 2021). "This study presented anti-metastatic effects of ATX against A172 human glioblastoma cells by inhibiting migration and invasion abilities with reducing MMP-2 and MMP-9 expressions as target molecules." (PMID 32711429, 2020). "It was shown that protease inhibitors have the potential of downregulating matrix metalloproteinase-9 (MMP-9) and MMP-2 during adipocyte differentiation and in glioblastoma cells." (PMID 33228205, 2020). "Recently, first studies confirmed a common interaction site of HSP27 in glioblastoma for both MMP2 and MMP9." (PMID 33287446, 2020). "In summary, our results demonstrated that BMAL1 as an anti-glioblastoma gene suppresses proliferation, migration, and invasion of U87MG cells by the downregulation of cyclin B1, p-AKT, and MMP-9." (PMID 32231148, 2020). "A recent study showed that the AhR exhibited tumor suppressor-like activity in established and patient-derived glioblastoma cells and genomic analysis showed that this was due, in part, to suppression of CXCL12, CXCR4 and MMP9." (PMID 32731514, 2020). "Knockout of CD147 in glioblastoma cells blocked the increased JNK signaling and the rise in secreted active MMP9 levels." (PMID 32033611, 2020). "As there were a series of downstream molecules of this pathway involved in proliferation, apoptosis, migration, and invasion of glioblastoma, we examined some of the downstream molecules, including: Cyclin D1, p21, Bcl-2, Bax, MMP-2, and MMP-9." (PMID 32596388, 2020). "Hypoxia and secreted macrophage soluble factors promote glioblastoma (GBM) invasiveness, though enhanced matrix metalloproteinase (MMP)-9 activity, promoting CCL4-CCR5 signalling between TAMs and U87 GBM tumour cells." (PMID 31835751, 2019). "Phospho-c-Jun activation by Anisomycin treatment in primary glioblastoma-derived cells attenuates the aggressive features of mesenchymal glioblastomas and leads to promoter methylation and downregulation of key mesenchymal genes (CD44, MMP9 and CHI3L1)." (PMID 28036297, 2017). "To determine the effect of miR-148a on GADD45A-mediated control of β-catenin, MMP-9, and EMT marker expression, we upregulated or downregulated miR-148a in IDH1WT or IDH1R132H glioblastoma cells overexpressing GADD45A." (PMID 28445981, 2017). "Upregulation of miR-148a only significantly increases β-catenin, MMP-9, and EMT marker expression in IDH1R132H glioblastoma cells by downregulating GADD45A." (PMID 28445981, 2017). "At human glioblastoma (T-98G) cells, MMP-2 and MMP-9 expression decreased with increased concentration of treatment, with the nutrient mixture being most effective, followed by green tea extract and then EGCG." (PMID 29181405, 2017). "Our previous study with other bee products proved that beebread and various honeys also inhibited the secretion of MMP9 and MMP2 in glioblastoma cells." (PMID 27647142, 2016). "A previous study indicated that biochanin A inhibited tumor invasion in human glioblastoma (U87MG) cells by suppressing the enzymatic activities of MMP-2 and MMP-9." (PMID 25398247, 2014). "A comparison of tumor subtypes demonstrated that CD133+ glioblastoma cells had a lower incidence of cell apoptosis in the tumor tissue and higher protein expression levels of Oct4, Sox2, PCNA, EGFR, Ang2, MMP2 and MMP9 compared with CD133− cells." (PMID 23251243, 2013).